LOX (lysyl oxidase)
Diseases named in the same sentence as LOX in open-access papers (continued):
Sharing a sentence is not in itself a finding about the gene and the disease.
cancer (continued). "Cancer cells can coax infiltrating fibroblasts to increase their ECM deposition, and the increased presence of lysyl oxidase (LOX) and transglutaminase in the TME results in increased cross-linking between collagen and elastin." (PMID 36765912, 2023). "Reducing LOX-mediated collagen crosslinking was sufficient to prevent tissue fibrosis and to increase ECM stiffness, focal adhesions, GF signaling, and cancer invasiveness in murine models of cancer." (PMID 37350937, 2023). "LOXL2 belongs to the lysyl oxidase (LOX) family and increasing evidence has shown its role in cancer cell invasion and metastasis." (PMID 37583701, 2023). "Therefore, LOX inhibitors may be of interest for modulating these phenomena and for controlling inflammation, gastrointestinal disorders, adverse cardiovascular reactions, and even cancer." (PMID 37571024, 2023). "The alignment of collagen fibres by lysyl oxidase (LOX) produced by cancer cells and CAF directs cancer cell migration and induces their proliferation." (PMID 37046716, 2023). "ROS also induces HIF-1α and lysyl oxidase (LOX), decreasing E-Cadherin levels and activating EMT and cancer cell migration." (PMID 35359388, 2022). "The expression of LOX/LOXL is considered an indicator of fibrosis and correlates to tissue stiffness in both fibrotic diseases and cancer." (PMID 35205728, 2022). "We show that chemotherapy induces the expression of LOX in CD8+ T cells, which in turn leads to ECM remodeling in the lungs, ultimately facilitating cancer cell seeding and metastasis." (PMID 34666995, 2022). "The prognostic signature that we constructed consisted of seven cancer driver genes (CDKN2C, HRAS, IRAK1, LOX, MYCN, NRAS, and PABPC1)." (PMID 36017503, 2022). "As a co-factor for cytochrome C oxidase and lysyl oxidase (LOX) proteins, copper regulates energy production to sustain cancer cell proliferation, invasion and metastasis." (PMID 36703728, 2022). "High LOX activity in various cancers contributes to increased ECM stiffness, and LOX overexpression promotes metastasis." (PMID 35740556, 2022). "Among these genes, for example, lysyl oxidase (LOX) family contributes to the angiogenesis, metastasis and formation of extracellular matrix (ECM) in carcinomas." (PMID 36211344, 2022). "Activated LOX increases the ECM stiffness, regulates cell migration, and promotes cancer malignancy." (PMID 34572752, 2021). "The metastatic potential of cancer can be enhanced by HIF-1α target genes, such as angiopoietin-like 4 (ANGPTL4), lysyl oxidase (LOX), and lysyl oxidase-like 4 (LOXL4)." (PMID 34575983, 2021). "Results show that the mRNA expression of lysyl oxidase (LOX) and GLUT-1, proteins involved in the crosslinking of collagen and glucose transporters, correlate well with an increased cancer grade evaluated by the Gleason score." (PMID 34357326, 2021). "In the recent past, LOX isoforms were identified as factors in the epithelial-mesenchymal transition (EMT), an event by which cancer cells gain motility and invasive mesenchymal cell properties." (PMID 34202354, 2021). "Secretion of ECM modifying enzyme families such as LOX, PLOD, and collagen among others can lead to higher invasiveness, migration, proliferation, and survival of cancer cells." (PMID 33828127, 2021). "Different protein isoforms, their intra and extracellular locations, the proteolytic cleavage status in the case of LOX and LOXL1, and other cellular events contribute to these different outcomes in cancer." (PMID 33669630, 2021). "In cancer settings, CAFs are main suppliers of fibrous collagens, fibronectin, elastin, laminin and ECM‐remodeling enzymes like collagen crosslinking lysyl oxidase (LOX), MMPs and tissue-inhibitors-of-metalloproteinases (TIMPs)." (PMID 34663337, 2021). "In this study, we found that the high expression of LOX is related to the ECM receptor interaction, cancer, Hedgehog, TGF-beta, JAK-STAT, MAPK, Wnt, and mTOR signaling pathways of GSEA." (PMID 34595188, 2021).
cancer (continued). "The lysyl oxidase (LOX) family, a type of secreted copper-dependent amine oxidases, is comprised of LOX and four LOX-like (LOXL) 1–4 isoforms and has been reported to be dysregulated in a number of different type cancers." (PMID 35126449, 2021). "LOX family members (LOX, LOXL1, LOXL2, LOXL3, LOXL4) reportedly mediate cell migration and metastasis of different cancers." (PMID 34815382, 2021). "GSEA showed that high LOX expression is related to ECM receptor interaction, cancer, Hedgehog, TGF-beta, JAK-STAT, MAPK, Wnt, and mTOR signaling pathways." (PMID 34595188, 2021). "Lysyl oxidase (LOX) is also a hypoxic gene that is involved in the migration and invasion of cancer cells." (PMID 32984033, 2020). "Of the global LOX network, 42 and 27 proteins were found in the MESO and OV datasets, respectively, with 24 proteins found in both cancer datasets." (PMID 33383846, 2020). "For example, LOX, LOXL2, LOXL3, and LOXL4 are overexpressed in more invasive cancers, such as triple negative breast cancers, inducing cancer cell invasion and metastasis." (PMID 32984031, 2020). "Increasing evidence has revealed that the lysyl oxidase, LOXL1 is involved in the malignant progression of cancer." (PMID 32912229, 2020). "Increases in LOX at the metastatic site increases ECM stiffness and facilitates cancer cell colonization." (PMID 31330786, 2019). "A mesenchymal signature (VIM, FN1, LOX, GPC6, ZEB1) was defined as the highest co-correlated mesenchymal marker set in Cancer Cell Line Encyclopedia (CCLE) NSCLC cell lines." (PMID 31581742, 2019). "Inhibiting LOX and lysyl oxidase-like 2 (LOXL2) and LOXL4 decreased metastasis in several cancer cell types." (PMID 29896451, 2018). "It has only been reported that LOX is regulated by HIF-1α under hypoxia and is induced by TGF-β in cancer cells, the mechanisms are still largely uncovered." (PMID 29472856, 2018). "Although the Tn antigen is prevalent in a variety of human cancers, only a few cancer cell lines robustly express the Tn antigen, including Jurkat, Tn4, LSC and LOX." (PMID 30115016, 2018). "For example, the lysyl oxidase (LOX), which is released from cancer and stromal cells, promotes γ-lysyl cross-bridges to stiffen the extracellular matrix (ECM)." (PMID 28198360, 2017). "To further confirm the subcellular localisation of LOX, we examined LOX expression in SW480, SW620 and HCT116 cancer cell lines using laser scanning confocal microscopy." (PMID 28947950, 2017). "For example, lysyl oxidase (LOX) expression is regulated by hypoxia-inducible factor (HIF), which responsible for the invasive properties of human cancer cells through focal adhesion kinase activity and cell to matrix adhesion under hypoxia conditions." (PMID 28423489, 2017). "Some HIF-1α upstream regulatory molecules such as NOTCH, mTOR (mechanistic target of rapamycin) and LKB1 can also regulate LOX expression indirectly through HIF-1α and mediates cancer progression." (PMID 28036074, 2016). "Other analyses indicated that LOX overexpression correlates with epithelial-mesenchymal transition (EMT) and activation of cancer stem cell pathways, such as the WNT and HEDGEHOG pathways." (PMID 27147578, 2016). "While the invasive mechanism mediated by LOX-HIF-1α has been poorly understood in EOCs, accumulating data in other cancer cells have indicated that multiple signaling mechanisms exist to regulate cell migration." (PMID 23545606, 2013). "In hypoxic cancer cells, HIF-1α binds to the hypoxia responsive element (HRE) in the promoter region of many target genes including LOX." (PMID 23545606, 2013). "Processed and enzymatically active LOX, in turn, stimulates Twist transcription, which mediates the MSC-triggered epithelial-to-mesenchymal transition (EMT) of carcinoma cells." (PMID 26237148, 2013). "LOX and NEO1 also appeared to be expressed by NP stromal cells, which would make them less suitable as cancer biomarkers." (PMID 20021671, 2009).
cancer (continued). "Furthermore, M2-polarized macrophages showed JMJD3-dependent transcriptional activation of lysyl oxidase (LOX), which contributes to extracellular matrix remodeling and cancer metastasis." (PMID 39858465, 2025). "Additionally, further exploration of the HIF-1α, LOX and ITGA5 axis in various cancer types and its therapeutic targeting will provide deeper insights into its roles in cancer progression and resistance to treatment." (PMID 39857068, 2025). "Lysyl oxidase (LOX) and lysyl oxidase-like protein (LOXL) are copper-dependent amine oxidases that catalyze the covalent cross-linking of collagen and elastin in extracellular matrix (ECM), which are related to the progression of cancer 336-338." (PMID 38725864, 2024). "However, increased expression of miR-29a hinders the spread of cancer cells to other parts of the body by targeting VEGFA, LOXL2, and LOX." (PMID 38915826, 2024). "This particular model provides predictions that could guide therapeutic treatments, such as inhibiting LOX production to slow down ECM remodeling, thus preventing the spread of cancer." (PMID 38495620, 2024). "Like LOX, it has been primarily reported for regulating EMT to promote cancer metastasis." (PMID 38962317, 2024). "Besides, copper serves as a crucial cofactor for several metalloenzymes involved in cancer metastasis, including SOD1, TGF-β, and LOX." (PMID 39691393, 2024). "Thus, lysyl oxidase isoenzymes (LOX and LOXL1-4) stabilize collagen networks and significantly contribute to cancer progression." (PMID 39594723, 2024). "Moreover, the lysyl oxidase (LOX) family members LOX, LOXL1, and LOXL4 have attracted much attention due to their critical role in cancer metastasis." (PMID 36910659, 2023). "In recent years, several preclinical and clinical studies have explored the efficacy of using the mechano-therapeutic approach in cancer; promising outcomes, including those of drugs targeting CTGF, TGF-β signaling, and LOX-mediated matrix stiffening, have been achieved." (PMID 36639658, 2023). "The top six upregulated gene sets in primary cancer by DGSS included fibrosis, cell motility, matrix metalloproteinase (MMP) remodeling, basement membrane, collagen family, and lysyl oxidase (LOX) remodeling at DGSS 9.84, 8.43, 7.79, 7.71, 7.55, and 7.20, respectively." (PMID 38062443, 2023). "As LOX is upregulated in response to chemotherapy, we next asked whether blocking LOX reverses the effects of chemotherapy-induced ECM remodeling and cancer cell adhesion." (PMID 34666995, 2022). "In cancer, lysyl oxidase inhibitors alone are not cytotoxic, but are thought to be ideal for combining with chemotherapies and/or immune therapies." (PMID 35205728, 2022). "Consistently, in a cancer cell adhesion assay, LOX-depleted plasma from PTX-treated mice failed to enhance EMT6 cancer cell seeding." (PMID 34666995, 2022). "LOX and LOXL proteins are proposed to promote EMT in cancer cells, and given Cu is a co-factor for their activity, this suggests that elevated Cu levels could serve as a driver of carcinogenesis." (PMID 36430490, 2022). "In addition, the M genes that exhibited dynamic compartment changes across the cancer cell lines were enriched in the biological process related to anatomical structure morphogenesis, including COL5A2, LOX, CDH2, ZEB1, and AXL (FDRdynamic = 1.22 × 10−8)." (PMID 35637517, 2022). "Functionally, LOX and LOXL2-dependent cross-linking of collagen and elastin has many roles, including increasing tissue stiffness and strength, promotion of cancer cell organization, activation of growth factors, and facilitation of matrix metalloprotease activity." (PMID 36430490, 2022).
cancer (continued). "FN1, significantly correlated with LOX expression in GBM in the present analysis, may also promote angiogenesis in cancer by providing a ridged structure for vessel development and signaling for endothelial cell migration." (PMID 36076905, 2022). "First of all, the collagen-related parameters (length, width, and density), the expression and distribution area of COL I and III, and the expression of COL I/COL III, COL I area/COL III area, LOX and LOXL2 in cancer tissues were higher than those in normal tissues." (PMID 34335820, 2021). "Besides chemoresistance, hypoxia contributes to the metastasis of NSCLC via upregulation of metalloproteinases (MMPs) and lysyl oxidase (LOX) involved in ECM remodeling and cancer cell migration." (PMID 34950592, 2021). "Effectively, this study showed that LOX activity and subsequent collagen cross-linking within the ECM could be altered through cancer induced changes to BMP1 production." (PMID 33513979, 2021). "In addition, in cancer tissues, the expression and area of COL I, COL I/COL III, and COL I area/COL III area and the expression of LOX and LOXL2 in patients with cold constitution were significantly higher than those in patients with heat constitution." (PMID 34335820, 2021). "Moreover, the mRNA expressions of COL I, LOX, and LOXL2 in the cancer tissues of cold-constitution patients were higher than those in heat-constitution patients." (PMID 34335820, 2021). "LOX enzymes, and specifically LOXL2, are critical for cancer progression and metastases." (PMID 33669630, 2021). "Given that lysyl oxidase inhibitors reduce the fibrotic ECM and desmoplasia in cancer, it is possible that initial treatment with lysyl oxidase inhibitors prior to administering chemotherapeutics will improve patient outcomes by priming the cancer microenvironment." (PMID 33513979, 2021). "One might think that the MPM specific expression pattern of the LOX and LOXL family needs to be further studied in the MPM cancer biology." (PMID 31921422, 2020). "LOX and LOXL2 have been well known to promote human cancer progression." (PMID 33095806, 2020). "The members of the lysyl oxidase (LOX) family are amine oxidases, which initiate the covalent cross-linking of the extracellular matrix (ECM), regulate ECM stiffness, and contribute to cancer progression." (PMID 33383846, 2020). "Importantly, targeting the signaling molecules downstream of LOX, FAK or Src, strongly sensitized cancer cells to chemotherapy when grown in collagen-embedded cultures or in vivo, showing the key role of these pro-survival signals in driving resistance." (PMID 32415208, 2020). "Similarly, the expression of the four MPM biomarker candidates LOX, LOXL1, LOXL2 and ZFPM2 were shown to be significantly increased in the MPM tissues when compared to the non-cancer patient samples." (PMID 31921422, 2020). "Moreover, the structural homolog of LOXL1, LOX, transcriptionally regulates SNAI2 expression by transactivating the SNAI2 promoter in human cancer cells." (PMID 33095806, 2020). "LOX and LOXL2 were significantly upregulated in RCC cell lines than other cancers." (PMID 32970930, 2020). "In contrast, in cancer treatment, reactive species might deactivate collagen modifying enzymes (e.g., P4HA, PLOD and LOX) or disturb the function of HIF." (PMID 31810265, 2019). "The role of LOX and LOXL2 has been well characterized in human cancers." (PMID 31121900, 2019). "Among the commonly upregulated LD+ associated genes in GBM cells and patient tumors, we found several hypoxia-related, key effectors of angiogenesis, macrophage recruitment and stromal remodeling in cancer (e.g. VEGF-A, TGF-β1, IL1β, ADM, IGFB3, LOX, CA9, THBS1, PLODs, ID2)." (PMID 31174567, 2019).
cancer (continued). "While augmented levels of collagen and LOX directly promote ECM stiffness and mechanically drive cell motility and proliferation, the exact role of hyaluronic acid in cancer metastasis remains unclear." (PMID 30287763, 2018). "Altogether, this study revealed that LOX expression is regulated by the EGFR pathway and this may account for the anti-cancer metastasis effects of silibinin, indicating LOX as a potentially therapeutic target for NSCLC treatment." (PMID 29472856, 2018). "However, it has only been reported that LOX expression is regulated by HIF-1α under hypoxia and is induced by TGF-β in cancer cells." (PMID 29472856, 2018). "LOX enzymatic activity promoted TWIST transcription, thereby mediating EMT of cancer cells." (PMID 28425924, 2017). "During cancer cell invasion, ECM is remodeled continuously by the cells through the secretion of proteins such as matrix metalloproteinases (MMPs) and lysyl oxidases (LOX)." (PMID 29038872, 2017). "This promiscuity, coupled with the lack of amenable sites for chemical modification, has rendered BAPN of little use for clinical drug development and detailed investigations into dissecting the differences in the functional role of LOX and/or LOXL2 in diseases such as cancer and fibrosis." (PMID 28199967, 2017). "Radiation did not affect LOX protein expression (neither localisation nor expression) in the two cell lines, consistent with the results obtained in the cancer tissues above." (PMID 28947950, 2017). "LOX is known to participate in critical biological functions that include cell migration, cell polarity, epithelial-to-mesenchymal transition (EMT) and angiogenesis, which fits with the increased LOX expression found in our carcinomas." (PMID 28143503, 2017). "Lysyl oxidase (LOX) and LOX-like protein 2 (LOXL2) produced by CAFs promote cross-linking of fibrillar type I collagen and result in matrix stiffening and consequent mechanotactic cues that support cancer cell invasion." (PMID 26954362, 2016). "LOX-mediated cross-linking of collagen IV recruits CD11b+ BMDC to the metastatic niche in the lungs, and these CD11b+ cells further remodel the ECM into a favorable home for extravasating cancer cells, e.g., by laying down the proteoglycan versican." (PMID 26539408, 2015). "Men with a low LOX score in the non-malignant prostate epithelium had significantly longer cancer specific survival than men with a high score." (PMID 26501565, 2015). "In addition, the expression levels of CD41, CD31 (MVD), BCAR1, VEGF, LOX and FAK were positively correlated with the clinical stages in the carcinoma (SCC, MC and CCC) samples (r=0.528, 0.613, 0.575, 0.575, 0.43, 0.571 and 0.589, respectively)." (PMID 25502723, 2015). "Moreover, we have now validated the direct interaction between the downregulated miR-29a and the upregulated LOX mRNA, which is also an EMT key player, suggesting another way for cancer cells to promote EMT." (PMID 25153510, 2014). "However, very intriguingly, another function of LOX in cancer cells was also recently reported, which is not dependent on the collagen arrangements." (PMID 36910659, 2023). "In vivo and in vitro data in mice and mouse cancer cells suggest a feedback pathway in which Gln LOX-PP has lost the ability to inhibit LOX expression, while wildtype Arg LOX-PP maintains a more normal LOX expression in a negative feedback pathway." (PMID 37298359, 2023). "The ECM remodeling by LOX and LOXL enzymes leads to collagen fiber realignment, bundling, and stiffening with dense collagen bundles that are frequently positioned perpendicular to the tumor, thereby allowing cancer cells to migrate via the fibers and invading the host tissue." (PMID 37490147, 2023). "Indeed, LOX has been reported to play a major role in ECM remodeling by establishing covalent crosslinks between collagen and elastic fibers that lead to ECM fibrosis and set the grounds for adherence and colonization of cancer cells." (PMID 35340765, 2022).